LTBP4 (latent transforming growth factor beta binding protein 4)
Diseases named in the same sentence as LTBP4 in open-access papers (continued):
Sharing a sentence is not in itself a finding about the gene and the disease.
chronic kidney disease (1 paper, 2021). Impairment of the renal function secondary to chronic kidney damage persisting for three or more months. "Herein, we report that LTBP4 is upregulated in patients with chronic kidney disease and fibrotic mice kidneys created by unilateral ureteral obstruction (UUO)." (PMID 34645813, 2021).
chronic lung disease (1 paper, 2016). According to the definitions of the American and British Thoracic Societies, including pulmonary functional tests, X-rays, and CT scans for items such as fibrosis, bronchiectasis, bullae, emphysema, nodular or lymphomatous abnormalities. "The association of LTBP4 SNPs with exercise performance in chronic lung disease could reflect LTBP4 involvement in either smooth and/or striated muscle, as well as in the lung parenchyma itself." (PMID 26918958, 2016).
Cirrhosis (1 paper, 2022). A chronic disorder of the liver in which liver tissue becomes scarred and is partially replaced by regenerative nodules and fibrotic tissue resulting in loss of liver function. "We found them to be upregulated in cirrhosis represented by the upregulation of PGDFRB, TGFB1 (TGF‐β1), TGFB1I1 (TGF‐β1 induced transcript 1 protein), TGFBI (TGF‐β induced protein ig‐h3), LTBP1, LTBP2, LTBP4, and ENG (transmembrane accessory receptor for TGF‐beta signaling)." (PMID 35579278, 2022).
colorectal adenoma (1 paper, 2025). An adenoma that arises from the colon or rectum. "LTBP4 double knockout mice develop colorectal adenomas and carcinomas, supporting the role of this gene in CRC predisposition." (PMID 41194282, 2025).
colorectal tumors (1 paper, 2025). "Supporting a causal role in CRC predisposition, LTBP4 KO mice develop colorectal tumors." (PMID 41194282, 2025).
diverticulosis (1 paper, 2020). "Little is known regarding its specific function in the intestine, however, recessive mutations of the LTBP4 gene caused malformations, including diverticulosis, enlargement, tortuosity, and stenosis at various levels of the intestinal tract." (PMID 33353204, 2020).
ductal carcinomas in situ (1 paper, 2013). "LTBP4 is downregulated in human and murine ductal carcinoma in situ and mammary adenocarcinomas." (PMID 23741501, 2013).
esophageal adenocarcinoma (1 paper, 2025). A malignant tumor with glandular differentiation arising predominantly from Barrett mucosa in the lower third of the esophagus. "A prior study showed that treatment of esophageal adenocarcinoma and squamous cell carcinoma cell lines with demethylating agents resulted in LTBP4 upregulation and decreased cancer cell migration." (PMID 41194282, 2025).
gastrointestinal carcinomas (1 paper, 2013). "In the present study we investigated the protein expression of LTBP4 in gastrointestinal carcinomas and in particular in neoplasias and preneoplasias of the esophagus." (PMID 23741501, 2013).
glomerular nephritis (1 paper, 2021). "In human donors with CKD, diagnosed with DMN and glomerular nephritis, LTBP4 was found to be upregulated in kidney tissues compared to that of patients with healthy kidneys, indicating that LTBP4 expression was associated with human TIF." (PMID 34645813, 2021).
leiomyoma (1 paper, 2007). A well-circumscribed benign smooth muscle neoplasm characterized by the presence of spindle cells with cigar-shaped nuclei, interlacing fascicles, and a whorled pattern. "LTBPs consist of LTBP-1 to LTBP-4 with LTBP-1 and -2 expression reported in leiomyomas." (PMID 17716379, 2007).
lung adenocarcinoma (1 paper, 2025). A carcinoma that arises from the lung and is characterized by the presence of malignant glandular epithelial cells. "According to the immune staining intensity comparisons provided by the HPA database, the expression levels of FABP4, GDF10, and LTBP4 were higher in normal samples, while the expression level of CBLC was higher in lung adenocarcinoma samples." (PMID 40766337, 2025).
muscle atrophy (1 paper, 2022). The loss of muscle tissue due to inactivity or disease. "In accordance with the functional classification of a GO term, a series of CGs was enriched into GO terms related to muscle development regulation, such as cell growth regulation (LTBP4) and skeletal muscle atrophy (MSTN)." (PMID 35883386, 2022).
non-small cell lung carcinoma (1 paper, 2021). A group of at least three distinct histological types of lung cancer, including non-small cell squamous cell carcinoma, adenocarcinoma, and large cell carcinoma. "In non-small-cell lung cancer (NSCLC), LTBP4 rs3786527 G>A was significantly related to lower all-cause mortality." (PMID 34071145, 2021).
Obesity (1 paper, 2023). Accumulation of substantial excess body fat. "Finally, a study in adult murine adipose stem cells demonstrates that while aging alone did not increase LTBP4, the confluence of aging and obesity increased LTBP4 expression." (PMID 37960979, 2023).
prostate carcinoma (1 paper, 2020). A carcinoma that arises from epithelial cells of the prostate gland. "The reference-free diagnostic panel used the ratio of relative expression of three mRNAs that are overexpressed (FOLH1, XBP1 and HPN) to five mRNAs that are underexpressed (ITSN1, GSTM4, LTBP4, NELL2, and CFD) in prostate cancer compared to normal tissue." (PMID 33172003, 2020). "However, two of the mRNAs, LTBP4 and NELL2, could not be measured in several prostate cancer and benign control samples." (PMID 33172003, 2020).
reflux esophagitis (1 paper, 2013). "Compared to normal esophageal tissue LTBP4 expression was also significantly downregulated in patient tissue of reflux esophagitis (38%) and chronic inflammation (39%), both risk factors for EAC." (PMID 23741501, 2013).
Right ventricular hypertrophy (1 paper, 2015). In this case the right ventricle is more muscular than normal, causing a characteristic boot-shaped (coeur-en-sabot) appearance as seen on anterior- posterior chest x-rays. "Ltbp4−/− mice displayed right ventricular hypertrophy in the heart, which Ltbp4S−/− mice do not." (PMID 25713297, 2015).
sarcoglycanopathies (1 paper, 2016). "Ltbp4 has recently been found to modify the phenotype of sarcoglycanopathies in mice." (PMID 27999547, 2016).
Sepsis (1 paper, 2025). Sepsis is defined as life-threatening organ dysfunction caused by a dysregulated host response to infection. "Rare variants in LTBP4 are significantly associated with the most severe pediatric sepsis phenotype (PedSep-D), while variants in PLA2G4E and CCDC157 show associations with this phenotype in suggestive significance." (PMID 41076474, 2025).
Skin Melanoma (1 paper, 2021). "In conclusion, the LTBP4-TGFβ1-Hippo-YAP1 axis is a critical pathway for the progression of skin melanoma." (PMID 35252214, 2021). "Therefore, LTBP4 regulates the progression of skin melanoma via the TGFβ1/Hippo/YAP1 signaling pathway." (PMID 35252214, 2021). "Therefore, we hypothesized that LTBP4 was a gene closely related to the occurrence and development of skin melanoma, and explored its related molecular mechanisms in this study." (PMID 35252214, 2021).
squamous cell carcinomas of the esophagus (1 paper, 2013). "Here we show that LTBP4 is also downregulated in adenocarcinomas and squamous cell carcinomas of the esophagus in vitro and in vivo." (PMID 23741501, 2013).
Tracheomalacia (1 paper, 2022). "Regarding the patient’s tracheomalacia, although some genes responsible for this trait are present in the region, such as ERF or LTBP4 on chromosome 19q13.2, none of the genes that were haploinsufficient in our patient seemed to be responsible for this feature." (PMID 35205257, 2022).
cancer (11 papers, 2010 to 2025). A tumor composed of atypical neoplastic, often pleomorphic cells that invade other tissues. "We found upregulation of factors such as FGF2, POSTN, and LTBP4 in classic morphology tumors, all of which are closely linked to activated cancer-associated fibroblasts (CAFs) and ECM remodeling." (PMID 41155518, 2025). "As opposed to the present results, others have reported a suppression of LTBP4 to cause cancer." (PMID 20459617, 2010). "In scRNAseq analysis, LTBP1 and LTBP2 were expressed dominantly in CAFs alone, while LTBP4 was strongly expressed in CAFs, in addition to pericytes and cancer cells." (PMID 40075643, 2025). "In adenocarcinoma and squamous cell carcinoma cell lines, demethylation treatment leads to upregulation of LTBP4 expression, resulting in reduced cancer cell migration." (PMID 34071145, 2021). "LTBP4 is an essential regulator of TGFβ signaling and is related to development, immunity, injury repair, and diseases, playing a central role in regulating inflammation, fibrosis, and cancer progression." (PMID 34071145, 2021). "However, given the dual role of the TGF-β signaling pathway in early and late-stage cancers, the role of LTBP4 in ACC tumorigenesis and metastasis requires further validation." (PMID 34359790, 2021). "Therefore, we first assessed the expression of LTBP4 levels in different cancer tissue microarrays by immunohistochemical staining." (PMID 23741501, 2013). "While it is unclear if these cancer‐based pathways also occur in age‐related pathologies and the shift from AKI to CKD, they offer a potential for greater mechanistic insight into LTBP4's role in mitochondrial alterations." (PMID 37960979, 2023). "Our results show that demethylation treatment leads to upregulation of LTBP4 in EAC and ESCC cell lines and higher LTBP4 expression reduces cancer cell migration." (PMID 23741501, 2013). "In distant lymph node metastasis, cancer cells also demonstrated no LTBP4 expression, while the surrounding mesenchymal tissue clearly showed LTBP4 expression." (PMID 23741501, 2013). "LTBP4 is not the only LTBP which is related to the formation of different cancer types." (PMID 23741501, 2013). "In addition to the LTBP4 constitutional monoallelic methylation, our analysis also identified mosaic constitutional methylation of the BRCA1 promoter in a male patient diagnosed with CRC at age 37 and with no family history of cancer." (PMID 41194282, 2025).
tumor (9 papers, 2009 to 2025). "CpG island 102 potentially regulates two LTBP4 transcripts expressed in colon epithelium, and the evidence gathered from tumor expression and methylation data suggests that methylation of this island drives global LTBP4 down-expression in CRC." (PMID 41194282, 2025). "In LUAD studies, WGCNA combined with immune-related genes identified four key hub genes: CBLC, FABP4, GDF10, and LTBP4, showing significant differential expression between tumor and normal samples." (PMID 40766337, 2025). "As a result, LTBP4 knockdown promoted tumor growth, whereas LTBP4 overexpression inhibited tumor growth." (PMID 35252214, 2021). "Our results suggest LTBP4 as a possible candidate gene for a biomarker panel for neoplasias and especially preneoplasias of esophageal tissue." (PMID 23741501, 2013). "Now we found that LTBP4 is downregulated in various human adenocarcinomas of the gastrointestinal tract, as well as in neoplasias and preneoplasias of the esophagus." (PMID 23741501, 2013). "LTBP4 downregulation has been reported in gastrointestinal cancers and other tumor types." (PMID 41194282, 2025). "Furthermore, we focused more precisely on LTBP4 expression in neoplasias and preneoplasias of the esophagus." (PMID 23741501, 2013). "It is possible that the dependency of FBN-1 and LTBP-4 on FN is primarily required in the early postnatal phase when blood vessels still undergo intensive remodeling and growth, or, alternatively, it is possible that this dependency is tissue specific (aorta versus tumor)." (PMID 30036393, 2018). "LTBP4 is a member of the TGF-β pathway, which can both inhibit tumor growth and promote progression in tumors, and its downregulation is common in advanced LUAD." (PMID 40766337, 2025). "Unsurprisingly, overexpression of LTBP4 increased the expression of LTBP4, cleaved caspase-3, and N-cadherin, but inhibited that of Ki67, E-cadherin, and YAP1 in tumor tissues of mice." (PMID 35252214, 2021). "In this study, tumor formation experiments in nude mice showed that YAP was highly expressed in the cytoplasm and nuclei of tumor tissues in mice transfected with LTBP4-silencing cells." (PMID 35252214, 2021). "Unfortunately, no tumor sample was available to perform somatic studies, such as assessment of a potential LTBP4 second hit and/or expression studies." (PMID 41194282, 2025).
connective tissue disease (3 papers, 2014 to 2025). "Mutations in human FBN1, FBN2, LTBP2, LTBP3 and LTBP4 have been associated with connective tissue disease in humans." (PMID 24703491, 2014).
adenocarcinoma (1 paper, 2013). A common cancer characterized by the presence of malignant glandular cells. "In detail, adenocarcinomas of esophagus showed 37%, of stomach 17%, of pancreas 9%, of small intestine 4% and of colon 22% LTBP4 expression." (PMID 23741501, 2013). "Analysis of patient tissues of various adenocarcinomas of the gastrointestinal tract revealed significant downregulation of LTBP4 in comparison to normal tissues of the same organ." (PMID 23741501, 2013).
infection (1 paper, 2025). The state of being infected such as from the introduction of a foreign agent such as serum, vaccine, antigenic substance or organism. "EFEMP1 and LTBP4 were additionally downregulated at 12 hpi and 24 hpi following Delta infection, while EGFL6 and FBLN5 showed consistent downregulation at both time points in Omicron infection." (PMID 41200555, 2025).
renal disease (1 paper, 2009). "Our data suggest that a similar interaction between TGFβ and LTBP-4 also occurs during renal disease." (PMID 19696925, 2009).
LTBP4 also shares sentences with these, for which no sentence is quoted: Ehlers-Danlos syndrome (2 papers); lung disorder (2); acute kidney injury (1); brain tumor (1); cardiac hypertrophy of (1); cardiovascular diseases (1); COVID-19 (1); diabetes (1); epithelial neoplasm (1); FLNB-Related Spectrum Disorders (1); hereditary cancer (1); Hermansky-Pudlak syndrome (1); inflammatory skin disease (1); Inguinal hernia (1); invasive mammary carcinomas (1); Joubert syndrome (1); left ventricular dilation (1); Loeys-Dietz syndrome (1); mammary adenocarcinoma (1); occipital horn syndrome (1); ovarian carcinoma (1); Peripheral pulmonary artery stenosis (1); pulmonary hypertension (1); squamous cell carcinoma (1); triple-negative breast carcinoma (1); Ureteral obstruction (1); valvular heart disease (1).